GUCY2EP (guanylate cyclase 2E, pseudogene)
Synonyms: GC-E; formerly GUCY2E
Gene: Transcribed unprocessed pseudogene on chromosome 11 (76,694,041 to 76,719,801, reverse strand). Ensembl gene ENSG00000204529.
Diseases named in the same sentence as GUCY2EP in open-access papers:
GUCY2EP is named in the same sentence as 7 diseases in open-access papers, as found by Europe PMC text mining. Sharing a sentence is not in itself a finding about the gene and the disease.
GUCY2EP shares sentences with these, for which no sentence is quoted: retinal diseases (2 papers); retinitis pigmentosa (2); ciliopathies (1); cone-rod dystrophy (1); Leber congenital amaurosis (1); retinal degeneration (1); Retinal dystrophy (1).